PRKAR2B (protein kinase cAMP-dependent type II regulatory subunit beta)
Diseases named in the same sentence as PRKAR2B in open-access papers (continued):
Sharing a sentence is not in itself a finding about the gene and the disease.
tumor (11 papers, 2011 to 2022). "Cd274 and Zbtb32 negatively regulate immunity, and S100a4, Rap1gap, Armc3, and Prkar2b promote tumor metastasis, This was consistent with the emergence of immunosuppression in the later stages of E. granulosus infection and with the hydatid cyst metastasis." (PMID 36569953, 2022). "PRKAR2B is a cAMP-dependent protein kinase (PKA) regulatory subunit that is abundantly expressed in various tumor tissues." (PMID 35663304, 2022). "The result showed that galactose also abrogated the tumour‐promoting role of PRKAR2B in cell proliferation." (PMID 33025691, 2020). "Moreover, tumour growth induced by PRKAR2B is largely glycolysis‐dependent indicative of the critical contribution of PRKAR2B in PCa glycolysis." (PMID 33025691, 2020). "Given that PRKAR2B promotes aerobic glycolysis in PCa cells and blocking glycolysis largely abrogates the tumour‐promoting effect of PRKAR2B, we conclude that PRKAR2B‐induced Warburg effect may be essential for prostate tumorigenesis." (PMID 33025691, 2020). "Importantly, inhibition of glycolysis by the glycolytic inhibitor 2‐deoxy‐d‐glucose (2‐DG) or replacement of glucose in the culture medium with galactose (which has a much lower rate than glucose entry into glycolysis) largely compromised PRKAR2B‐mediated tumour‐promoting effect." (PMID 33025691, 2020). "The type II beta regulatory subunit of PKA, cAMP-dependent protein kinase type II–beta regulatory subunit (PRKAR2B), is highly expressed in CRPC and is involved in tumor proliferation and metastasis." (PMID 35335890, 2022). "A new study has revealed that PRKAR2B enhanced the expression level of hypoxia-inducible factor 1α (HIF-1α), a crucial moderator of the Warburg effect, thereby promoting tumor growth." (PMID 35335890, 2022). "The corresponding genes of these three DMPs were mesothelin (MSLN), protein kinase cAMP-dependent type II regulatory subunit beta (PRKAR2B), and msh homeobox 1 (MSX1), all of which correlated with tumor development, malignancy, and treatment." (PMID 33995018, 2021). "We further demonstrate a reciprocal regulation between PRKAR2B and HIF‐1α and this loop have a critical role in the Warburg effect and tumour growth." (PMID 33025691, 2020). "The type II beta regulatory subunit of protein kinase A (PKA), PRKAR2B, is highly expressed in castration‐resistant prostate cancer (CRPC) and contributes to tumour growth and metastasis." (PMID 33025691, 2020). "Our results showed that (a) PRKAR2B enhances PCa cell glycolysis, (b) PRKAR2B is able to upregulate HIF‐1α protein level, (c) HIF‐1α transcriptionally induces PRKAR2B expression in PCa; (d) PRKAR2B‐mediated tumour growth in PCa cells is glycolysis‐dependent." (PMID 33025691, 2020). "The result showed that PRKAR2B knockdown significantly retarded xenograft tumour growth of DU145 cells, while PRKAR2B overexpression promoted xenograft tumour growth of LNCaP cells." (PMID 33025691, 2020). "In addition to MCM2-7 complex, other proteins in the cluster also influenced the growth and division of tumor cells by participating in the cell cycle such as RRM2, PRKAR2B, and MKI67." (PMID 33200655, 2020). "Because glycolysis can enable tumour growth by providing intermediates for biosynthesis and NADPH production, we tested whether glycolysis is needed for PRKAR2B‐mediated growth advantage." (PMID 33025691, 2020). "Importantly, tumour growth advantage induced by PRKAR2B could be largely abrogated by HIF‐1α knockdown, suggesting the importance of PRKAR2B‐HIF‐1α loop in PCa development." (PMID 33025691, 2020). "In addition, the activities of check-point, tumor-infiltrating lymphocytes (TIL), chemokine C-C-Motif receptor (CCR), T-cell coinhibition, and type II interferon (IFN) response were markedly enhanced in the GDN subjects with low PRKAR2B expression or subjects with high TGFBI expression." (PMID 35663304, 2022).
cancer (9 papers, 2012 to 2024). A tumor composed of atypical neoplastic, often pleomorphic cells that invade other tissues. "The upregulated expression of Nucleolin, Prkcsh, Prkar2b, and Zbed3 and the downregulated expression of Nfatc4 promoted cancer cell proliferation, migration, and invasion by activating the Wnt/β-Catenin signaling pathway." (PMID 34848840, 2021). "In this study, we for the first time uncovered a new role of PRKAR2B in regulating cancer cell glycolysis." (PMID 33025691, 2020). "PRKAR2B is involved in mitotic cell cycle transition and response to cancer-related drug clozapine." (PMID 35033028, 2022). "And most of the 24 DEPs (CDK1, SFN, PRKAR2B, MKI67 and MDK involved in the cell cycle; LOXL2, P4HA1, P4HA2, SPRX, DES, PRPH and CALML3 involved in construction and regulation of extracellular matrix; IL33 and EHD3 may involve in immune) were linked to cancer hallmarks." (PMID 33200655, 2020). "We computationally predicted PTPRF, PRKAR2B, MAP4K3, and RICTOR to be responsible for the cancer phenotype, and each of them was experimentally validated by means of cell death or migration assay." (PMID 26336805, 2015). "However, this study also shows unexpected up-regulation of crucial genes and kinases (e.g., ERBB4, PLCβ4, PRKAR2B, and PDGFA) whose roles in cancer development and progression are crucial." (PMID 36430510, 2022). "Furthermore, our results suggest that four of these genes - ADCK2, PRKAR2B, TRIB2 and TRPM7 - seem to regulate HIF-1α accumulation in multiple cancer cell lines." (PMID 22355351, 2012).
hematologic malignancies (1 paper, 2015). "Cohorts of Prkar1a+/−, Prkar2a+/−, Prkar2a−/−, Prkar2b+/− and wild type (WT) mice have been observed between 5 and 25 months of age for the development of hematologic malignancies." (PMID 26608815, 2015). "We studied Prkar2a- haploinsufficient (Prkar2a+/−), Prkar2b- haploinsufficient (Prkar2b+/−), Prkar2a−/− KO, as well as double-heterozygote (Prkar1a+/−x Prkar2a+/-) F1 mice for the development of hematologic malignancies." (PMID 26608815, 2015).
infection (1 paper, 2023). The state of being infected such as from the introduction of a foreign agent such as serum, vaccine, antigenic substance or organism. "So, in two different host-parasite combinations, infection-induced increases in the miR-34c-3p lead to a reduction in prkar2b transcripts and an increase in host PKA activity independent of fluxes in cAMP." (PMID 36847534, 2023). "We identified prkar2b (cAMP-dependent protein kinase A type II-beta regulatory subunit) as a novel miR-34c-3p target gene and demonstrate how infection-induced upregulation of miR-34c-3p repressed PRKAR2B expression to increase PKA activity." (PMID 36847534, 2023). "First, we confirmed that infection with P. falciparum does indeed lead to increased amounts of intraerythrocyte miR-34c-3p, and then we demonstrated that this increase correlated with a reduction in the abundance of prkar2b mRNA and increased PKA activity." (PMID 36847534, 2023). "Finally, we extend our observations to Plasmodium falciparum-parasitized red blood cells, where infection-induced augmentation in miR-34c-3p levels led to a drop in the amount of prkar2b mRNA and increased PKA activity." (PMID 36847534, 2023). "We confirmed that infection of red blood cells by P. falciparum leads to increased amounts of miR-34c-3p and demonstrated that inhibition of miR-34c-3p binding to its cognate seed sequence raised prkar2b transcript levels and reduced infected red blood cell PKA kinase activity." (PMID 36847534, 2023). "Here, we describe how infection by two important animal and human parasites, Theileria annulata and Plasmodium falciparum, induce changes in infected host cell miR-34c-3p levels to regulate host cell PKA kinase activity by targeting mammalian prkar2b." (PMID 36847534, 2023).
PRKAR2B also shares sentences with these, for which no sentence is quoted: acromegaly (1 paper); brain edema (1); Carney complex (1); ciliopathy (1); glioma (1); Hypertension (1); myocardial infarction (1); pancreatic ductal adenocarcinoma (1); Parkinsonism (1); prostate (1); Retinitis pigmentosa 67 (1); sarcopenia (1); Splenomegaly (1); squamous cell carcinoma (1); type 2 diabetes (1).